TPH2 (tryptophan hydroxylase 2)
Diseases named in the same sentence as TPH2 in open-access papers (continued):
Sharing a sentence is not in itself a finding about the gene and the disease.
Anxiety (continued). "Since GABA receptors have been shown to mediate fast synaptic inhibition in neural circuits implicated in the behavioral responses to stress (Paredes and Ågmo 1992), Arfgef3 upregulation may contribute to the anxiety and stress-related behavior observed in Tph2+/− mice." (PMID 37542675, 2023). "Our study showed that interactions between CTQ score and TPH2 gene polymorphism were found regarding the anxiety score of behaviour and the GMV of the right posterior parietal thalamus (RPPTha), which was identified as an important mediator between the anxiety and CTQ scores." (PMID 38093326, 2023). "Moreover, it could also modulate biosynthesis of certain neurotransmitters—such as serotonin through tryptophan hydroxylase 2—and neurotrophic factors, thereby modulating mood and anxiety-like behaviors." (PMID 37566598, 2023). "Here, Tph2−/− females entered the center less frequently, traveled shorter distances in the center, and defecated more than Tph2+/+ females (all p < 0.05), reflecting increased immobility and anxiety-like behavior as well as increased stress-related autonomic reactivity in the OF." (PMID 25716307, 2015). "Furthermore, significant sex × genotype interactions for grooming (data not shown) and the number of defecations indicate reduced anxiety-like behavior to be specifically prominent in Tph2−/− males, which groomed and defecated less thanTph2+/+ mice (both p < 0.05)." (PMID 25716307, 2015). "Previous studies showed that Tph2 null mutant mice not only exhibit severe growth retardation during early development, but also a number of behavioral alterations in adulthood, most notably in the emotional domain, being characterized by decreased anxiety-related behavior, but enhanced impulsivity." (PMID 25901271, 2015). "In addition to the action on anxiety and depressive-like behaviour, the reduction of GSK3β activity also antagonizes the effects of a reduced 5-HT synthesis on social behaviour and aggression in mice expressing mutant TPH2." (PMID 22826345, 2012). "Increased expression of tph2, htr1a, and slc6a4 in the cDRD of HFD-fed rats is consistent with previous studies implicating the cDRD in chronic (even lifelong) anxiety-like states, and vulnerability to future stress exposures in adulthood." (PMID 38705984, 2024). "Finally, we sought to determine whether female Tph2+/− mice resemble features of Tph2+/− males in the broader context of emotional resilience to environmental challenges found in the modified swim test (modFST) and in tests for anxiety-like behavior in naïve and stressed female Tph2+/− mutants." (PMID 35326487, 2022). "The Tph2−/− mice exhibited depressive-like behavior in TST and anxiety-related behavior in the marble burying test." (PMID 36010683, 2022). "Adult Pet-1 null mice have severe deficits in 5-HT1aR, TPH2, and SERT in the dorsal raphe nucleus region, and show elevated anxiety-like behavior and aggression." (PMID 36703746, 2022). "The double KO Tph1/Tph2−/−mice showed depressive-like behavior in TST and anxiety-related behavior in the marble burying test but antidepressive-like behavior in the forced swim test (FST) with reduced levels of 5-HT in the brain and periphery." (PMID 36010683, 2022). "In this study, the effects of Paeonia lactiflora on PMS anxiety and on the expressions of ERβ, TPH-2, and SERT in DRN of rats with PMS anxiety were investigated." (PMID 32219134, 2020). "This is supported by effects of Mv to decrease Tph2 mRNA expression among CDR/SD mice in the DRD, an anxiety-related subregion of the DR." (PMID 33469429, 2020). "Paeonia lactiflora extract can upregulate the expression of ERβ and TPH2 in the DRN and downregulate the expression of SERT, thus regulating PMS anxiety." (PMID 32219134, 2020). "In accordance with previously reported data, we observed decreased anxiety in the EPM, as indicated by the time spent on the open arms, in Tph2-/- mice." (PMID 31133792, 2019).
Anxiety (continued). "In order to assess the relationships between TpH2 gene expression in the DRN and cognitive, anxiety-like, and depressive-like behaviors, we correlated the level of TpH2 mRNA in each subregion of the DRN with the evaluated behaviors." (PMID 28008302, 2016). "Nevertheless, the effects of TTC9A−/− on estrogen regulation of TPH1, TPH2 and 5-HTT which influences anxiety-like behaviors will remain an interesting topic for future investigation." (PMID 27869229, 2016). "Previous studies have shown that E2 increases TpH2 mRNA in specific subregions of the DRN in Ovx rats, and that this increase is critical for ameliorating anxiety-like and depressive-like behaviors." (PMID 28008302, 2016). "To conclude, our findings do not support an association between SLC6A4 or TPH2 methylation and 5-HTT or 5-HT4 brain levels or measures of early life stress, anxiety or depressive symptoms." (PMID 38802956, 2024). "More studies are needed to rule out a role of SLC6A4 and TPH2 methylation as biomarkers for environmental stress, depressive or anxiety symptoms." (PMID 38802956, 2024). "Based on the earlier reported findings, we assumed that TPH2 G‐703T modulated all three phenotype traits: considering the protective effect of anxiety on ADHD, we hypothesized a positive effect on anxiety (i.e., GG > T+)." (PMID 33523602, 2021). "After intervention with the Paeonia lactiflora extract, the number, morphology, and protein expression of positive cells of ERβ, TPH2, and SERT were restored and close to the control group, demonstrating that Paeonia lactiflora extract can regulate PMS anxiety." (PMID 32219134, 2020). "Similar to Tph2-deficient mice, Vmat2sert-cre CKO mice do not show increased anxiety-like behaviors, despite the reduced level of 5-HT in the brain." (PMID 28713247, 2017). "Therefore, in the present study, we evaluated and compared the effects of CEE and E2 administration on TpH2 mRNA expression in the DRN, and on a battery of cognitive, anxiety-like, and depressive-like behaviors in Ovx Sprague Dawley rats." (PMID 28008302, 2016). "Supporting these differences to be important for the behavioral differences, serotonin depletion obtained by the tryptophan hydroxylase-2 inhibitor p-chlorophenylalanine eliminated them by reducing anxiety in “anxious” but not “non-anxious” rats." (PMID 25716782, 2015). "Whereas, maternal separation (MS) stress increased anxiety- and depressive-like behaviors of WT mice, with no detectable behavioral changes in TPH2 KI mice." (PMID 25964750, 2015). "It is possible that abnormality of this form of behavior, rather than altered anxiety, accounts for the increased marble burying in TPH2 and TPH1/TPH2 DKO mice." (PMID 18923670, 2008). "Moreover, chronic administration of corticosterone, which induces a chronic anxiety-like state, induces an increase in tph2 mRNA expression in the DR, although these effects are not restricted to the cDRD region." (PMID 38705984, 2024). "However, as the Tph2‐/‐ mouse also demonstrates increased aggression and decreased anxiety‐like behavior, it is not known to what extent the Tph2‐/‐ mouse reflects ADHD symptomatology." (PMID 33523602, 2021). "Finally, immunization with M. vaccae prevented stress-induced increases in expression of serotonergic genes, including Tph2 and Slc6a4, in the DRD, a subregion of the dorsal raphe nucleus that has been well-characterized as responsive to stress- and anxiety-provoking stimuli." (PMID 33469429, 2020). "In contrast, reduced raphe TPH2 expression was reported in Wistar rats displaying a low degree of exploratory behavior; this study, however, did not employ the EPM paradigm but a test based on exploration of novel and familiar objects and assumed to reflect both motivation and anxiety." (PMID 25716782, 2015).
Anxiety (continued). "The key findings of this study are firstly that environmental stressors, when applied during the early postnatal period, will induce anxiety- and depressive-like behaviors through dysregulations of the serotonergic system in WT mice, with no detectable effects in TPH2 KI mice." (PMID 25964750, 2015). "MS WT mice also had significantly decreased exploratory measures in the zero maze compared to non-MS WT mice (ps < 0.001) and exhibited similar levels of anxiety-like behaviors to non-MS and MS TPH2 KI mice, which in turn were not significantly different from each other." (PMID 25964750, 2015). "Conditional knocking out PET-1 in adult mice abrogated Tph2 but not VMAT expression in specific sets of raphe 5-HT-producing neurons, leading to enhanced anxiety behavior." (PMID 26402365, 2015). "In the present study, we show a TPH2 inhibitor, p-CPA, to reduce anxiety-like behavior in anxious LO rats but not in nonanxious HO animals, hence eliminating the behavioral difference between the 2 groups." (PMID 25716782, 2015). "Interestingly, the knockdown of TLR4 in Tph2 neurons, which are highly expressed in the DRN, reduces anxiety-like behavior in male but not female mice, suggesting that TLR4 in Tph2 neurons regulates anxiety-like behavior in a sex-dependent manner." (PMID 41459223, 2025).
bipolar disorder (17 papers, 2009 to 2025). A disorder of the brain that causes unusual shifts in mood, energy, activity levels and the ability to carry out day-to-day tasks. "Supporting a developmental origin of these changes, several linkage studies have described an association between bipolar disorder and single nucleotide polymorphisms in genes such as TPH2, HTR1A, HTR2A, HTR2C or SLC6A450–55." (PMID 30087403, 2018). "There are several functional polymorphisms in the TPH2 gene and some are associated with the risk of bipolar disorder." (PMID 20723248, 2010). "Interestingly, a TPH2 gene polymorphism or TPH2 activation has been reported in patients with depressive and bipolar disorder." (PMID 31763490, 2019). "We also show a remarkable correspondence between the hippocampal transcriptomic signatures of Tph2 KO and that observed in neurons from bipolar disorder patients." (PMID 30087403, 2018). "Accumulating evidence has proposed that several functional polymorphisms of TPH2 gene are associated with psychiatric disorders including major depressive disorder (MDD), attention deficit hyperactivity disorder (ADHD), schizophrenia, and bipolar disorder." (PMID 32346385, 2020). "Importantly, remarkable correspondence between the transcriptomic profile of the Tph2 mutant hippocampus and neurons from bipolar disorder patients was observed." (PMID 30087403, 2018). "Moreover, the polymorphisms of TPH-2 have been shown to be associated with ADHD, obsessive–compulsive disorder, and bipolar affective disorder." (PMID 27871272, 2016).
schizophrenia (16 papers, 2010 to 2025). A major psychotic disorder characterized by abnormalities in the perception or expression of reality. "Bellivier and Chaste conducted associative studies of the role of the SNVs of the gene TPH2 with suicidal behavior among patients suffering from schizophrenia." (PMID 35328011, 2022). "One TPH2 SNP has been associated with the severity of positive psychotic symptoms in patients with schizophrenia." (PMID 25073638, 2014). "Furthermore, the SNP of the TPH2 gene was associated with the development of paranoid schizophrenia, multiple sclerosis, and panic disorders." (PMID 31817010, 2019). "Finally, dysregulation of glutamatergic and serotoninergic genes, such as Grina, Htra1, and Tph2, has been reported in several NDs, and Esyt1 is increased in the brain from schizophrenia patients." (PMID 35268026, 2022). "To assess the role of TPH2 gene variability in the etiology of psychiatric diseases we performed cDNA sequence analysis of TPH2 transcripts from human post mortem amygdala samples obtained from individuals with psychiatric disorders (drug abuse, schizophrenia, suicide) and controls." (PMID 20126463, 2010). "However, ERVWE1 had weak negative correlations with SERT and TPH2 in schizophrenia patients." (PMID 37990254, 2023).
autism (11 papers, 2007 to 2025). Persistent deficits in social interaction and communication and interaction as well as a markedly restricted repertoire of activity and interest as well as repetitive patterns of behavior. "Among them are genes encoding the serotonin transporter 5-HTT (transmission disequilibrium at the 5-HTT locus in 86 autism trios), and a rate-limiting enzyme for serotonin synthesis TPH2 (two intronic SNPs rs4341581 and rs11179000 at introns 1 and 4, respectively, have been associated with autism)." (PMID 23935565, 2013). "The TPH2-KO rat may thus serve as a valuable tool for investigating the role of serotonin in behavioural disturbances associated with neuropsychiatric disorders, such as autism." (PMID 40594285, 2025). "Building on previous scientific studies in mice, we examined behavioural phenotypes of TPH2-KO rats to evaluate their potential as a serotonin-depleted autism model." (PMID 40594285, 2025). "Although TPH2-KO rats exhibit phenotypes mimicking certain autism-related behaviours, the extent to which these findings translate to human autism should be interpreted cautiously." (PMID 40594285, 2025). "This research highlights the serotonergic system’s role in socio-communicative and repetitive behaviours, establishing the TPH2-KO rat model as a valuable tool for exploring the neurobiological underpinnings of autism and related disorders." (PMID 40594285, 2025). "TPH is the rate limiting enzyme in the synthesis of 5-HT, the expression of TPH2 gene decreased in the brain of patients with autism, and the defect of TPH2 gene will affect the shape of 5-HT neuronal circuit." (PMID 35937893, 2022). "Stereotypic and repetitive behaviors are influenced by 5-HT, and initial studies report an association of TPH2 alleles with childhood-onset obsessive-compulsive disorder (OCD) and with autism." (PMID 17346350, 2007). "TPH2-KO rats demonstrated distinct patterns of USVs compared to WT controls, supporting the presence of communication deficits in TPH2-KO rats, which aligns with the core symptoms of autism." (PMID 40594285, 2025). "The correlation between TPH2 and autism is also confirmed from the behavioral level." (PMID 35937893, 2022). "TPH2 gene variants are unlikely to contribute to autism or to the presence/absence of prominent repetitive behaviors in our sample, although an influence on the intensity of these behaviors in autism cannot be excluded." (PMID 17346350, 2007). "To test the hypothesis that serotonin dysfunction can contribute to the core symptoms of autism, we analyzed mice lacking brain serotonin (via a null mutation in the gene for tryptophan hydroxylase 2 (TPH2)) for behaviors that are relevant to this disorder." (PMID 23139830, 2012). "These initial studies yielded promising evidence supporting TPH2 and GLO1 roles as autism vulnerability genes." (PMID 17346350, 2007). "This study utilises a rat model lacking the central serotonin-synthesising enzyme tryptophan hydroxylase 2 (TPH2) to investigate the effects of brain serotonin depletion on core autism-related behaviours." (PMID 40594285, 2025). "Only one report has provided preliminary evidence for the involvement of TPH2 variants in autism, whereas following research has failed to confirm the association for either TPH1 or TPH2." (PMID 19949574, 2009). "The present study provides evidence that TPH2 and GLO1 gene variants do not contribute significantly to autism pathogenesis in our sample, while GLO1 could seemingly exert a protective effect in unaffected siblings." (PMID 17346350, 2007). "Not systematically tested in connection with blood levels of 5-HT nor in SERT-oriented models of autism, MAOA and its enzymatic partners however deserve interest, in connection with other concerned agents, including SERT, 5-HT receptors, and TPH2 among a large family of neurotransmission regulators." (PMID 33262691, 2020).
mood disorder (8 papers, 2010 to 2025). A cognitive disorder a disturbance in which the person's mood is hypothesized to be the main underlying feature. "Whether mood disorders linked to insufficient tph2 in the brain can be ameliorated by load-induced enhancement of serotonergic signaling will be the next step to investigate." (PMID 24416346, 2014). "Moreover, several polymorphisms in TPH2, which had previously been linked to mood disorders, were shown to lead to reduced expression of TPH2." (PMID 23935583, 2013). "Indeed, most previous studies linking peripheral SLC6A4 or TPH2 methylation to stress-related phenotypes were based on patients with mood disorders or individuals who were exposed to intense environmental stress." (PMID 38802956, 2024). "It is necessary to evaluate whether the observed upregulation of tph2 increases serotonin transmission in the key action circuit of the brain, which constitute a basis for attenuating mood disorders by physical activities." (PMID 24416346, 2014). "Especially, TPH-2 is expressed in peripheral tissues of the brain, which is important in the regulation of mood disorders, whereas TPH-1 is not significantly expressed in the brain." (PMID 30854015, 2019).
alcohol dependence (7 papers, 2009 to 2023). Physical and psychological dependence on alcohol. "Zill has chosen 20 SNPs covering the second isoform of the tryptophan hydroxylase gene (TPH2) to search for any role of the gene in pathophysiology of alcohol dependence or alcohol dependence - related phenotype suicidal behavior." (PMID 25415204, 2014). "Interestingly, similar to Tph2−/− mice, in the Sardinian alcohol-preferring rat line, an animal model used to study alcohol dependence, an enhancement of ethanol drinking and reduction in the depression-like state were also accompanied by deficits in 5-HT function in the brain." (PMID 35269497, 2022). "As previously suggested, Tph2−/− mice hold promise as a new model for ethanol dependence and exploring non-serotonergic drugs for the treatment of alcoholism." (PMID 37923824, 2023).
Cognitive impairment (7 papers, 2010 to 2025). Abnormal cognition is characterized by deficits in thinking, reasoning, or remembering. "This study highlights the great opportunity the Tph2-kd rat model offers to study inter-individual susceptibilities to develop cognitive impairment following mild variations of brain serotonin in otherwise healthy individuals." (PMID 38732220, 2024). "The molecular signature of the behavioral stress response of Tph2+/− mice identifies risk genes in pathways leading to cognitive impairment and emotional dysregulation as well as related neuropsychiatric disorders." (PMID 37542675, 2023). "Our findings indicated that cognitive impairment and hopelessness were associated with TPH2 rs7305115 SNP among MDD+suicide patients." (PMID 20738857, 2010). "But, we found that HDRS scores of cognitive impairment and hopelessness were associated with TPH2 rs7305115 genotypes among MDD+suicide (p = 0.035 and p = 0.032)." (PMID 20738857, 2010). "Dysfunctions in TPH2 are likely to influence serotonergic functioning and thus play a role in the pathogenesis of emotional and cognitive disorders, given the wide functions of 5-HT." (PMID 33178100, 2020). "Taken together, these data suggested that maintaining normal TPH2 levels in DRN is antidepressant and improves cognitive impairment in 5×FAD mice." (PMID 39044270, 2024).